KIT (KIT proto-oncogene, receptor tyrosine kinase)
Diseases named in the same sentence as KIT in open-access papers (continued):
Sharing a sentence is not in itself a finding about the gene and the disease.
leukemia (continued). "Unlike KIT in leukemia cells, that in cer-C6-treated GIST-T1 assumed an immature glycosylated form, indicating that KIT is complex-glycosylated in GIST after reaching lipid rafts." (PMID 31484543, 2019). "Since BFA and M-COPA bind not only to the ARF1-GBF1 complex but also to other complexes, the blockers affect KIT trafficking in a manner independent of ARF1-GBF1 inhibition in the leukemia cells used in this study." (PMID 31484543, 2019). "Thus, these discoveries motivate us to consider a combination trial between TQ and inhibitors for KIT and FLT3 signaling in ongoing studies for improving therapeutic outcomes in leukemia." (PMID 28415607, 2017). "In addition to regulating apoptosis, genetic ablation of PAK1 enhanced the survival of KIT D814V bearing mice in secondary transplants, indicating that targeting PAK1 inhibits the growth/survival of KIT D814V bearing leukemia initiating cell (LIC)." (PMID 26158763, 2015). "This inhibitor was tested to be exclusively specific for PDGFRβ in leukemia and vascular smooth muscle cells, not targeting PDGFRα and c-KIT." (PMID 23900414, 2013). "However, the role of c-KIT in leukemia stem cells (LSCs) and the BCL-2 inhibitor resistance is not well explored." (PMID 36232694, 2022). "These include mutations in genes known to cooperate with CBF-rearrangements [e.g. NRAS (n = 6), KRAS (n = 4), FLT3 (n = 2), KIT (n = 3), ZBTB7A (n = 2)] as well as in genes, which have not been described to be mutated in CBF leukemia so far (e.g. ZFHX4, NFE2, HERC1)." (PMID 31896782, 2020). "Therefore, we hypothesized that PPFIA1 contributes to leukemia growth through an axis involving PARP1, P65, and KIT." (PMID 30825668, 2019). "Furthermore, the expression level of both KIT mRNA and proteins is much higher in the CBFL, with either wild-type or mutant KIT, than in leukemia cells negative for CBF rearrangements." (PMID 31817911, 2019). "Interestingly, both CBF leukemia fusion proteins and miR-17, which targets RUNX1-3′UTR, negatively affect a common core RUNX1-miRNA mechanism that forces myeloid cells into an undifferentiated, KIT-induced, proliferating state." (PMID 25612891, 2015). "MiRNA-based deregulation of RUNX1 expression could explain why non-CBF leukemias are often characterized by molecular defects, such as KIT upregulation, typically produced by CBF karyotypic abnormalities." (PMID 23344057, 2013). "In addition, the antitumor effect of PF was evaluated using a panel of cell lines, including a mutant KIT-expressing leukemia cell line (Kasumi), wild type KIT-expressing cell lines (Colo320DM and H128), and KIT-negative cell lines (HeLa, Capan-1, and MDA-MB-231)." (PMID 37704840, 2023). "Our finding that all LSC sub-populations recapitulate the heterogeneity of the original leukemia sample implies that the sub-populations defined by CSF2RB, IL1RL1, and KIT are likely not to be organized in a strict hierarchical differentiation scheme." (PMID 30742053, 2019).
mastocytosis (184 papers, 2005 to 2026). A clonal myeloproliferative neoplasm characterized by the proliferation and accumulation of neoplastic mast cells in one or multiple organs or organ systems. "This c-KIT mutation gene was found in 80% of adult mastocytosis patients but has been reported in varying prevalences in children, going from 0% to 83%." (PMID 41597149, 2026). "Recent studies have provided insights into the genetic mutations (especially mutations in the KIT gene) that contribute to the pathogenesis of mastocytosis." (PMID 40951188, 2025). "Systemic mastocytosis (SM)-derived EVs transfer functional KIT to hepatic stellate cells, activating them and promoting mastocytosis-associated liver pathology." (PMID 41168571, 2025). "On the other hand, KIT signaling can enhance MITF expression in mastocytosis, a rare disorder caused by activating KIT mutations, most commonly KIT D816V, leading to excessive mast cell proliferation and accumulation in tissues." (PMID 40343114, 2025). "Mastocytosis is caused by a clonal expansion of mast cells, most commonly triggered by the KIT D816V mutation present in over 90% of adult patients." (PMID 40963125, 2025). "Testing for KIT mutation and beta-glucosidases was ordered to assess for mastocytosis and Gaucher’s disease, respectively, both of which can manifest with bleeding, osteonecrosis, and hepatosplenomegaly were negative." (PMID 40557010, 2025). "Given the high similarity in clinical presentation and the co-occurrence of KIT mutations, we also propose that these diseases be classified as a genetically highly homologous disease entity, namely ovarian germ cell tumors/mastocytosis with KIT mutations." (PMID 41568380, 2025). "Avapritinib is a novel tyrosine kinase inhibitor targeting KIT mutations that is approved for systemic mastocytosis but doesn’t currently have an established role in the treatment of AML." (PMID 40576687, 2025). "Mastocytosis is driven by a clonal expansion of mast cells, commonly triggered by the KIT D816V mutation which is present in over 90% of adult patients." (PMID 40963125, 2025). "Given the consistent co-occurrence of KIT mutations in previously reported similar cases, we propose the recognition of a distinct disease entity: ovarian germ cell tumor/mastocytosis with KIT mutations." (PMID 41568380, 2025). "KIT mutation is a marker of mastocytosis and exists in more than 90% of systemic mastocytosis cases." (PMID 41568380, 2025). "Familial mastocytosis is a specific form of the disease in which mostly germline KIT mutations are detected in affected family members." (PMID 38338679, 2024). "The results show that our patient cohort correlated ancestrally with the European group, which is reflective of our NIH population group with mastocytosis and the KIT M541L variant." (PMID 39037378, 2024). "Specifically, ours is the first case/control study to show a significant association with the KIT M541L variant in both pediatric and adult patients with mastocytosis when patients are stratified by disease variant and genotype at the KIT M541L locus." (PMID 39037378, 2024). "Overall, these results indicate that KIT M541L genotypes are associated with mastocytosis, as well as specific phenotypic groups within the mastocytosis cohort, namely, systemic disease with MPCM and adult onset." (PMID 39037378, 2024). "This study uniquely examines the prevalence and impact of the KIT M541L variant in both adult and pediatric patients with mastocytosis further stratified by disease variant." (PMID 39037378, 2024). "It is also interesting to note that studies of KIT mutations performed on cells other than mast cells show that about 30% of individuals with mastocytosis have a multilineage myeloid and/or lymphoid involvement of hematopoiesis." (PMID 39456668, 2024).
mastocytosis (continued). "More than 90% of patients affected by mastocytosis are characterized by a somatic point mutation of KIT, which induces ligand-independent activation of the receptor and downstream signal triggering, ultimately leading to mast cell accumulation and survival." (PMID 39456668, 2024). "Here, we report the first known case of radiation-associated CM with a mutation in c-KIT and describe the favorable prognosis of radiation-associated mastocytosis." (PMID 39143718, 2024). "Among the 10 described cases in the literature, only two prior diagnoses of mastocytosis with a c-KIT mutation have been identified." (PMID 39143718, 2024). "KIT variants harbouring mutations that keep the receptor constitutively active have been associated with neoplastic MCs and MC disorders such as mastocytosis." (PMID 38938682, 2024). "KIT M541L has been reported in unaffected parents of patients with CM, suggesting that alone this variant is likely insufficient to cause mastocytosis." (PMID 39037378, 2024). "Individuals carrying the CC homozygous genotype at the KIT M541L locus are predicted to have an almost 5-fold increased risk of mastocytosis onset compared to individuals with any other KIT 541 genotype." (PMID 39037378, 2024). "More than 90% of mastocytosis cases are characterized by a somatic point mutation of KIT, the majority of which induces ligand-independent activation of the receptor and downstream signal activation, ultimately leading to mast cell proliferation and survival." (PMID 39456668, 2024). "Ultimately, as she fulfilled only two minor criteria for systemic mastocytosis (elevated tryptase and a positive c-KIT D816V mutation), she was diagnosed with cutaneous mastocytosis." (PMID 39143718, 2024). "The cause of mastocytosis is mutational hyperactivation of KIT, the tyrosine kinase receptor for stem cell factor, which mast cell development and survival depend on." (PMID 36752151, 2023). "These activating KIT variants, mostly somatic, have been associated with human malignancies, including mast cell proliferative disorders such as mastocytosis." (PMID 37025992, 2023). "IL-6 is produced by MC, and patients with mastocytosis have increased IL-6 plasma levels probably related to the constitutional activation of the KIT signaling pathway caused by D816V mutation, as described in in vitro models." (PMID 37108232, 2023). "Regarding the pathogenesis of mastocytosis, somatic, gain-of-function point mutations within KIT play crucial role in the development of the disease." (PMID 38066824, 2023). "Mastocytosis is caused by activating mutations in KIT, a gene encoding for Stem Cell Factor (SCF) receptor." (PMID 37108232, 2023). "Mastocytosis is a heterogeneous disease associated with the clonal proliferation of mast cells (MC) driven commonly by the oncogenic KIT mutation (D816V)." (PMID 36834926, 2023). "Mastocytosis, a clonal proliferation of mast cells, results from a mutation in the KIT pathway and presents with cutaneous symptoms, and in some cases, patients present with gastro-intestinal symptoms." (PMID 36970068, 2023). "Occasionally, mastocytosis associated with tuberous sclerosis and gastrointestinal stromal tumors, with germline or somatic KIT mutations, has been reported." (PMID 38066824, 2023). "Asp816Val (D816V) KIT mutation is the hallmark of mastocytosis, and it is located in the catalytic domain of the receptor, leading to mast cell proliferation and survival." (PMID 36834926, 2023). "Activating mutations of KIT, a receptor tyrosine kinase, are central to mastocytosis pathogenesis, enabling the proliferation and survival of abnormal mast cells in affected tissues." (PMID 36834926, 2023). "KIT gene mutations in Ewing sarcomas are rare; however, they are much more frequent in other neoplasms, namely mastocytosis." (PMID 38222235, 2023).
mastocytosis (continued). "Among the described diseases, a mutation in a single gene caused mastocytosis, thrombotic thrombocytopenic purpura, Gaucher disease, and paroxysmal nocturnal hemoglobinuria (KIT, ADAMTS13, GBA1, and PIG-A genes, respectively)." (PMID 36766791, 2023). "Three patients with AML1::ETO fusion gene-positive AML had a KIT mutation and one of the three patients had systemic mastocytosis." (PMID 36629738, 2023). "Mastocytosis is the pathologic process of the accumulation of abnormal mast cells in different organs, mostly driven by KIT mutations, and can present as cutaneous mastocytosis, systemic mastocytosis (SM), and mast cell sarcoma." (PMID 38067330, 2023). "Mutations in the juxtamembrane (JM) domain of KIT such as V560G (exon 11) are rare in mastocytosis but frequent in gastrointestinal tumors (GIST)." (PMID 37025992, 2023). "Mastocytosis is characterized by the accumulation of neoplastic mast cells (MCs) in tissues, most often due to an acquired activating mutation in the KIT protein, which leads to increased proliferation and survival of MCs." (PMID 35596520, 2022). "It has been demonstrated that SM cases with multilineage KIT mutation cluster more frequently with advanced mastocytosis (AdvSM) than indolent cases." (PMID 35745657, 2022). "Overall, KIT mutations other than KIT D816V can be found in up to 4–5% adults and one third of children with mastocytosis." (PMID 35626091, 2022). "Gain-of-function mutations in KIT have been found in germ cell tumors, mastocytosis, AML and GIST in humans." (PMID 36396684, 2022). "Given the structural similarity of FLT3 and KIT, midostaurin also inhibits D816V‐mutated KIT and has been approved for aggressive systemic mastocytosis." (PMID 36254250, 2022). "More recently, biological studies have identified germline or acquired activating KIT mutations also in childhood-onset mastocytosis, confirming its clonal nature." (PMID 35574357, 2022). "Mastocytosis is associated in most cases with somatic gain-of-function point mutations of the c-KIT gene." (PMID 35574357, 2022). "Both TET2 and KIT mutation are required to provoke a mastocytosis-like disease in mice, although hypermethylated DNA signatures, consistent with TET2 loss of function, have only been described in TET2-deficient mast cells." (PMID 35393954, 2022). "In childhood mastocytosis, KIT mutations are found more frequently in other loci (exons 8, 9, 11); in up to 25%, no KIT mutations (KIT wild-type) are detectable at all." (PMID 35028497, 2022). "The first relates to the fact that it was derived from a patient cohort studied in a reference mastocytosis center in which assessment of multilineage involvement of hematopoiesis by the KIT mutation is readily accessible." (PMID 35344302, 2022). "The accumulation of atypical MCs in mastocytosis is almost exclusively caused by point mutations in KIT, which encodes the transmembrane tyrosine kinase protein (CD117) that binds stem cell factor, a major growth factor for MCs." (PMID 35876458, 2022). "In pediatric cutaneous mastocytosis, mast cell accumulations are only found on the skin, and the KIT mutation plays a subordinate role with regard to further clinical management." (PMID 35028497, 2022). "On that basis, KIT D816V ASqPCR in PB has been incorporated into a recent diagnostic algorithm of pediatric mastocytosis." (PMID 33806685, 2021). "There is still scarce research on non-KIT epigenetic-associated mutations in various types of mastocytosis." (PMID 33803981, 2021). "A multicenter French study revealed that 86% of 50 children with mastocytosis had different mutations in KIT detected in lesional skin." (PMID 33806685, 2021). "Since then, additional reports have been published, and the mutated c-KIT has been found in mastocytosis, seminoma, sarcoma, among others." (PMID 34439864, 2021). "The main causes of mastocytosis are hypermorphic mutations in the proto-oncogene KIT (also referred to as c-kit)." (PMID 33925601, 2021).
mastocytosis (continued). "Non-KIT mutations were less frequent but still comprised a substantial proportion of the mastocytosis patients." (PMID 33803981, 2021). "Such KIT mutations have been identified in aberrant mast cells of virtually all adult- and the majority of pediatric-onset mastocytosis patients." (PMID 33708774, 2021). "The contribution of KIT and other mutations to the altered production of VEGFs and ANGPTs in patients with different forms of mastocytosis remains to be investigated." (PMID 33687603, 2021). "Generally, the KIT D816V mutation is less frequently detected in cases of childhood-onset mastocytosis than in adult patients (approximately 40% vs. >80%)." (PMID 34063170, 2021). "The mechanisms underlying the correlation between KIT mutation and clinical phenotypes of pediatric mastocytosis are poorly understood." (PMID 33806685, 2021). "Although it is accepted that there is a limited KIT mutation spectrum in pediatric mastocytosis, it is still a clonal disease." (PMID 33918305, 2021). "In more than 95% of patients, the KIT activating mutation D816V is identified as the underlying cause of mastocytosis, the clonal expansion of mast cells is found as the basis of the onset and severity of allergic reactions." (PMID 34066544, 2021). "Heritability associated with germline mutations of KIT is extremely rare in mastocytosis, and these germline KIT mutations occur in different gene regions such as N822I, F522C, K509I, S451C, R634W, Del 419, A533D, S476I, among others." (PMID 33806685, 2021). "Of note, rare cases of mastocytosis with germline KIT mutations associated with tuberous sclerosis and gastrointestinal stromal tumors were reported." (PMID 33806685, 2021). "Mastocytosis occurring in childhood is an exception in that KIT D816V mutation is observed in only 40% of cases, other KIT mutations in 35% of cases, and wild-type KIT in 25% of cases." (PMID 34681933, 2021). "Mastocytosis is caused by mutations in KIT, the tyrosine kinase receptor for stem cell factor, on which mast cell development and maintenance depends." (PMID 33708774, 2021). "FLT3 is one of the most frequently mutated genes in AML, while KIT oncogenic mutations occur in 80–90% of mastocytosis." (PMID 32708273, 2020). "The KIT inhibitor, avapritinib, is effective for the treatment of systemic mastocytosis with KIT D816 mutations." (PMID 32999426, 2020). "Another KIT inhibitor imatinib is ineffective on KIT D816V observing almost all mastocytosis but is effective on KIT mutations in GISTs." (PMID 32023940, 2020). "In contrast, we observed that the KIR2DL4 protein expression was lacking in the human neoplastic mast cell line HMC1.2 expressing mutated KIT and deficient in FcεRI expression, and that nine of 15 cutaneous mastocytosis samples were KIR2DL4-negative." (PMID 32023940, 2020). "Mastocytosis is strongly linked to somatic mutations in theKIT gene (and especially theKIT D816V mutation) coding for the tyrosine kinase receptor KIT, which lead to constitutive activation." (PMID 31824655, 2019). "Mastocytosis is caused by an activating mutation of KIT that leads to uncontrolled proliferation and accumulation of MCs with heterogeneous clinical manifestations ranging from cutaneous and advanced forms with poor prognosis." (PMID 31355297, 2019). "Taken as a whole, these observations strongly suggest the additional involvement of one or more germline or somatic mutations or polymorphisms in genes other than KIT; these would act synergistically withKIT mutations in the development of mastocytosis." (PMID 31824655, 2019). "KIT D816V is a hallmark of mastocytosis, a rare disease caused by the accumulation of functionally defective mast cells." (PMID 31143189, 2019). "Mastocytosis is a disorder resulting from an abnormal mast cell (MC) accumulation in tissues that is often associated with the D816V mutation in KIT, the tyrosine kinase receptor for stem cell factor." (PMID 29643855, 2018).